AP5S1 (adaptor related protein complex 5 subunit sigma 1)
Description:
As part of AP-5, a probable fifth adaptor protein complex it may be involved in endosomal transport. According to PubMed:20613862, it is required for efficient homologous recombination DNA double-strand break repair.
Synonyms: C20orf29; FLJ11168
Tractability: Antibody: UniProt places it where antibodies can reach, with high confidence. PROTAC: ubiquitination databases record sites on it; its protein half-life has been measured.
Gene: Protein-coding gene on chromosome 20 (3,811,384 to 3,828,838, forward strand). Ensembl gene ENSG00000125843.
Subcellular location: Cytoplasm, cytosol; Late endosome membrane; Lysosome membrane
Subcellular location (Human Protein Atlas): Cytosol; Nucleoplasm
Gene Ontology:
Molecular function: protein binding
Biological process: double-strand break repair via homologous recombination; endosomal transport; lysosome organization; vesicle-mediated transport
Cellular component: AP-type membrane coat adaptor complex; cytosol; late endosome; lysosome; AP-5 adaptor complex; late endosome membrane; lysosomal membrane
Genetic constraint (gnomAD): Loss-of-function variants: 13 observed, 13.46 expected, observed/expected ratio (o/e) 0.97, 90% interval 0.63 to 1.53. The upper end of that interval is the gene's LOEUF score, 1.53, which puts it in group 6 of 6, group 1 being the genes least tolerant of losing a copy. Missense variants: 292 observed, 279.95 expected, observed/expected ratio (o/e) 1.04, 90% interval 0.95 to 1.15. Synonymous variants: 132 observed, 124.82 expected, observed/expected ratio (o/e) 1.06, 90% interval 0.92 to 1.22.
Homologues: Orthologues: chimpanzee AP5S1 (100% identical), macaque AP5S1 (98% identical), dog AP5S1 (91% identical), rabbit AP5S1 (88% identical), pig AP5S1 (88% identical), mouse Ap5s1 (86% identical), guinea pig AP5S1 (86% identical), rat Ap5s1 (64% identical), zebrafish ap5s1 (46% identical), tropical clawed frog ap5s1 (46% identical).